CASK (calcium/calmodulin dependent serine protein kinase)
Diseases named in the same sentence as CASK in open-access papers (continued):
Sharing a sentence is not in itself a finding about the gene and the disease.
microcephaly (continued). "The CASK-neurexin interaction was traditionally suggested to be mediated by the binding of a few residues at the end of neurexin’s cytoplasmic tail to CASK’s PDZ domain, and missense variants located on the PDZ domain may be linked to developmental disorders with/without microcephaly." (PMID 36092876, 2022).
Intellectual disability (29 papers, 2012 to 2025). "CASK mutations are also known to cause other neurological phenotypes such as intellectual disability, developmental delay, and ophthalmological abnormalities." (PMID 40422238, 2025). "Interactions between CASK and the partner proteins must be examined to understand the mechanisms of CASK-associated intellectual disability and epilepsy and to develop new therapeutic strategies." (PMID 37628707, 2023). "It is reported that CASK gene variant can mainly lead to these phenotypes: severe intellectual disability, microcephaly with pontine and cerebellar hypoplasia (MICPCH, OMIM: 300,749) in women." (PMID 35550617, 2022). "Variants in the CASK gene result in a wide range of observed phenotypes in humans, such as FG Syndrome 4 and intellectual disabilities." (PMID 35668446, 2022). "TBR1 binds to CASK, which is a membrane-associated guanylate kinase playing a key role in intellectual disability." (PMID 32948248, 2020). "Heterozygous loss-of-function mutations in the X-linked CASK gene have been associated with severe intellectual disability and with ASD." (PMID 32948248, 2020). "While missense mutations corresponding to functional change of the CASK protein causes non-syndromic intellectual disability or FG syndrome, a decrease in the normal expression appears to correlate with the manifestation of MICPCH." (PMID 28783747, 2017). "The only annotated disease variant we tested in CASK was the kinase domain variant R28L causing FG Syndrome, an X-linked disorder causing intellectual disability, physical anomalies and developmental delays." (PMID 28542158, 2017). "The synaptic scaffolding protein CaM associated serine kinase (CASK) is also important for learning and memory, as mutations in CASK result in intellectual disability and neurological defects in humans." (PMID 27583167, 2016). "Mutations in human CASK have recently been shown to result in intellectual disability and neurological defects suggesting a role in plasticity and learning possibly via regulation of CaMKII autophosphorylation." (PMID 25009461, 2014). "Missense mutations in CASK are frequently identified in boys with mental retardation and are often associated with structural defects in the brain, as well as the head, neck, and face region." (PMID 24505460, 2014). "The synaptic scaffolding protein CASK (calcium (Ca2+)/calmodulin (CaM) associated serine kinase) is also important for learning and memory, as mutations in CASK result in intellectual disability and neurological defects in humans." (PMID 24062638, 2013). "However, patient 3 presented only a mild intellectual disability (see Patients and Methods), in striking contrast to the other patients reported with CASK loss-of-function variants." (PMID 36765386, 2023). "These CASK functional roles may at least partially account for the brain developmental deficit and intellectual disability observed in patients with CASK variants." (PMID 36092876, 2022). "Generalized loss of CASK function, whether through disruption of protein-protein interactions or through absence of protein, is likely responsible for the developmental and intellectual disabilities seen in all individuals with CASK mutations." (PMID 24505460, 2014). "The severity of the disease in patients with a CASK deletion was very similar to patients with intragenic mutations regarding motor and intellectual disability, epilepsy, MRI anomalies and hearing and visual defects, even when the deletion involved nine other genes." (PMID 22452838, 2012). "Mutations in the gene encoding CASK have been linked to intellectual disability and ASD, which implies the pathway downstream of the CASPR2-CASK complex is important for disease pathophysiology." (PMID 36340692, 2022). "Herein, we describe a novel missense variant (c.1882G>C) in CASK, which was detected in two male siblings displaying a MICPCH phenotype, as well as in their mother and grandmother, both with mild intellectual disabilities." (PMID 36092876, 2022).
Intellectual disability (continued). "CASK is a calcium/calmodulin-dependent serine protein kinase involved in intellectual disability." (PMID 36860299, 2023). "For example, human orthologs to fly genes CASK (CASK), Mnb (DYRK1A), Dlg-1 (DLG1), Cdc42 (CDC42), Fmr1 (FMR1, FXR1/2), trio (TRIO), Nedd4 (NEDD4L/NEDD4) and CamKII (CAMK2A/B/D) have been linked to intellectual disability." (PMID 37759179, 2023). "Intellectual disability (ID) is been commonly observed both in males (96.1%) and females (93.5%; p = 0.4315, males vs. females; statistically not significant between gender, Chi-square test) affected by CASK-related disorders." (PMID 37628707, 2023). "For example, we found a CASK c.2147A>C:p.(His716Pro) variant in a patient (P91) with nystagmus and no intellectual disability." (PMID 35052368, 2021). "A null variant in CASK (calcium/calmodulin-dependent serine protein) induced variable intellectual disability, with or without nystagmus." (PMID 35052368, 2021). "Therefore the spectrum of phenotypes associated with CASK mutations is very large in males, from lethality or severe neurologic impairment with PCH to isolated intellectual disability." (PMID 22452838, 2012). "The wide distribution of missense mutations of CASK in the patients of epilepsy, which is also observed in the case of intellectual disability, indicates that epilepsy and intellectual disability may be due to multiple molecular mechanisms related to different functional domains of the CASK protein." (PMID 37628707, 2023). "In addition, CASK hypomorphic inherited mutations have been described in patients, mainly male, affected with intellectual disability and not featuring MICPCH." (PMID 22452838, 2012).
Nystagmus (10 papers, 2012 to 2023). Rhythmic, involuntary oscillations of one or both eyes related to abnormality in fixation, conjugate gaze, or vestibular mechanisms. "It has proven difficult to perform definitive genotype–phenotype correlation studies of CASK variants, although it has been suggested that variants in the C-terminus are more likely to be correlated with nystagmus due to CASK’s interaction with FRMD7." (PMID 35406695, 2022). "A critical analysis of the relationship between nystagmus and specific CASK variants, however, indicates that nystagmus is incompletely penetrant and may be cerebellar in origin." (PMID 35406695, 2022). "Nystagmus can be associated with CASK variants in all regions of the protein." (PMID 35406695, 2022). "To date, CASK-related disorders comprise various developmental disorders such as MICPCH, X-linked intellectual disability, FG syndrome, pediatric epilepsy syndrome, ophthalmologic phenotypes (such as nystagmus), hearing impairment, and autism spectrum disorders." (PMID 37628707, 2023). "Hypomorphic CASK missense variants are often associated with X-linked intellectual disability (XLID) with or without nystagmus, which can be found in both males and females." (PMID 36092876, 2022). "The CASK gene is involved in X-linked dominant intellectual disability with or without nystagmus (MIM 300422)." (PMID 36393831, 2022). "However, a recent study found that mutations within the C-terminal region of CASK disrupt the interaction, which is crucial for correct development of oculomotor control between FRMD7 and CASK, leading to nystagmus." (PMID 33732697, 2021). "Typically, MICPCH is associated with loss-of-function (i.e., nonsense or frameshift) mutations of the CASK gene, while XLID with or without nystagmus appears to be associated with hypomorphic (i.e., missense) mutations of the CASK gene." (PMID 37628707, 2023). "Patient 2, with a nonsense mutation of c.846C>G (p.Tyr282*) in CASK, had early psychomotor developmental delay, mild facial abnormalities and MICPCH, without nystagmus, epileptic encephalopathy, or ASD." (PMID 36168867, 2022). "In summary, patient 1, with a nonsense mutation of c.82C>T (p.Arg28*) in CASK, had early psychomotor delay, and MICPCH, without nystagmus, special facial abnormalities, epileptic encephalopathy, or ASD." (PMID 36168867, 2022). "Several groups have reported CASK mutations in male patients with other phenotypes: FG syndrome and X-linked mental retardation (XLMR) with or without nystagmus." (PMID 22452838, 2012). "CASK-related disorders are classified into two primary phenotypes, MICPCH, and XLID with or without nystagmus." (PMID 37628707, 2023).
developmental delay (9 papers, 2017 to 2025). "However, variants throughout CASK are associated with developmental delay and MICPCH, demonstrating the difficulty of genotype–phenotype correlations at a protein structure level." (PMID 35406695, 2022). "This includes severe brain malformations, mental retardation, seizures, psychomotor developmental delay, and cardiac, urinary, and gastrointestinal abnormalities (the associated genes are: DNML, CEP290, CASK, PIGN)." (PMID 36421828, 2022).
epilepsy (9 papers, 2012 to 2023). A brain disorder characterized by episodes of abnormally increased neuronal discharge resulting in transient episodes of sensory or motor neurological dysfunction, or psychic dysfunction. "Considering that each functional domain exerts a unique biological function by associating with different partner proteins, it is reasonable to assume that there are multiple molecular mechanisms underlying the ID or epilepsy in CASK-related disorders." (PMID 37628707, 2023). "Among them, a main phenotype of epilepsy by CASK deficiency was late-onset drug-resistant spasms, some of which developed into developmental and epileptic encephalopathy." (PMID 37628707, 2023). "For example, in our cohort, two children with intractable post-neonatal epilepsy had variants in the CASK and CACNA1H genes." (PMID 33846556, 2022). "This concept of neurocircuit interference may provide new insights into the neurocircuit mechanism of female-restricted intellectual disability and epilepsy in CASK-related disorders, as well as other X-linked disorders." (PMID 37628707, 2023). "Furthermore, CASK is the gene responsible for Ohtahara syndrome, one of the most severe and earliest forms of epilepsy, and mutation in CASK resulted in a synapse dysfunction and induced epileptic episodes." (PMID 36606143, 2022). "In addition, CASK mutations are associated with growth retardation, optic nerve hypoplasia/ atrophy, epilepsy, sensorineural deafness and hypotonia often resulting in scoliosis." (PMID 27036546, 2016). "It has also been reported that patients with CASK-related disorder can be affected by Ohtahara syndrome, West syndrome, absences epilepsy, Lennox-Gastaut syndrome, and myoclonic epilepsy." (PMID 37628707, 2023). "As previously discussed, epilepsy phenotypes were observed more frequently in males with CASK-related disorders than in females." (PMID 37628707, 2023). "No trend has been observed in pathogenic mutations of the CASK gene related to ID and epilepsy to date." (PMID 37628707, 2023). "The increased excitability of neuronal circuits caused by the loss of CASK gene expression may explain the pathogenesis of epilepsy in patients with CASK-related disorders." (PMID 37628707, 2023). "This sexual difference in epilepsy incidence may be due to the proportion of CASK-expressing cells in the brain." (PMID 37628707, 2023). "Although the neuron-specific CASK heterozygous knockout mice did not exhibit any major phenotype, the complete neuronal CASK knockout mice exhibited pronounced growth retardation and epilepsy, and both are symptoms of CASK-related syndromes." (PMID 27036546, 2016). "It has been suggested that CASK may act via its interaction with Tbr1 (Hsueh, Wang, Yang, & Sheng, 2000), but in a murine model, disruption of the CASK‐Tbr1 interaction did not produce any structural defects or epilepsy." (PMID 32696595, 2020).
FG syndrome (7 papers, 2012 to 2023). "Pathogenic mutations in CASK have been identified in brain malformation, Opitz-Kaveggia syndrome, and developmental disorders." (PMID 34006971, 2021). "Changes at position 28 from arginine are present in CASK orthologs; in fact, in a representative Placozoan species (T. adhaerens), residue 28 is a leucine, the residue in hCASK identified as a mutation that causes FG syndrome." (PMID 24505460, 2014). "Mutations in CASK are associated with mental retardation as well as structural defects in the brain such as pontocerebellar hypoplasia, Ohtahara syndrome, FG syndrome with corpus callosum agenesis, tetralogy of Fallot, and autism spectrum disorders." (PMID 24505460, 2014). "There was, however, little evidence of defective neuronal migration in other contexts of CASK-linked disorders that were not MICPCH but were often attributable to missense variants in CASK, such as normocephalic boys with XLID and even in FG syndrome." (PMID 35406695, 2022).
and cerebellar hypoplasia (6 papers, 2016 to 2026). "Microcephaly with pontine and cerebellar hypoplasia (MICPCH) syndrome is a neurodevelopmental disorder caused by the deficiency of the X-chromosomal gene CASK." (PMID 37190086, 2023). "Missense mutations affecting the CASK-Neurexin interaction have been identified in patients with cerebellar hypoplasia." (PMID 37190086, 2023). "To investigate the molecular mechanism by which CASK deficiency causes cerebellar hypoplasia, we examined the effects of CASK mutations on the survival of CG cells in mice." (PMID 37190086, 2023). "These mutations are located at the binding interface with Liprin-α2, suggesting that the CASK-Liprin-α2 interaction may be involved in the pathophysiology of cerebellar hypoplasia in MICPCH syndrome." (PMID 37190086, 2023). "Furthermore, mutations in CASK that have been identified in MICPCH syndrome patients with cerebellar hypoplasia have been reported to reduce the binding affinity of CASK to Liprin-α2." (PMID 37190086, 2023). "Therefore, our findings also provide a valid framework for the investigation of non-CASK related cerebellar hypoplasia." (PMID 27036546, 2016). "In silico structural analysis using machine learning-based software revealed that these missense mutations disrupt the binding interface with Liprin-α2, suggesting that CASK-Liprin-α2 interaction may be involved in the pathophysiology of cerebellar hypoplasia in MICPCH syndrome." (PMID 37190086, 2023).
MICPCH syndrome (6 papers, 2012 to 2025). "To investigate the molecular mechanism underlying cerebellar hypoplasia in MICPCH syndrome, we first studied postnatal day 0 (P0) CASK-/Y mice." (PMID 40422253, 2025). "Nonetheless, our work provides a molecular framework that bridges CASK deficiency and cell death signaling in the cerebellum and opens the door for targeted therapeutic strategies in MICPCH syndrome." (PMID 40422253, 2025). "In this study, we investigated the molecular mechanism by which CASK deficiency induces cerebellar hypoplasia in MICPCH syndrome." (PMID 37190086, 2023). "MICPCH syndrome is one of the pathogenic phenotypes of CASK-related disorders, for which there are differences between human phenotypes and mouse models." (PMID 37628707, 2023). "Male patients with MICPCH syndrome caused by CASK somatic mosaic deficiency have also been reported." (PMID 37190086, 2023). "We investigated the molecular mechanism that causes cerebellar hypoplasia in MICPCH syndrome using CASK KO mice and found that missense mutations in the CaMK domains identified from human patients affect CG cell survival in the dissociated culture system." (PMID 37190086, 2023). "A better understanding of the role of CASK in the pathophysiology of neurodevelopmental disorders may provide insights into novel therapeutic and diagnostic strategies for MICPCH syndrome and other neurodegenerative diseases." (PMID 40422253, 2025). "We found a CASK mutation through CMA in a female patient with MICPCH syndrome." (PMID 33584783, 2020). "Due to the perinatal lethality of CASK knockout, we evaluated the effect of JNK inhibition on the cerebellar hypoplasia In Vivo in female CASK heterozygote knockout mice, whose genetic background is representative of the majority of MICPCH syndrome." (PMID 40422253, 2025). "In conclusion, JNK-IN-8 suppresses the cell death and activation of the ROS pathway in CASK-KO CG cells in both in vitro and in vivo models, suggesting its potential as a therapeutic strategy for cerebellar neurodegeneration in MICPCH syndrome." (PMID 40422253, 2025). "Female CASK heterozygote KO mice replicate the progressive cerebellar hypoplasia observed in MICPCH syndrome." (PMID 37190086, 2023). "In this study, we used CASK knockout (KO) mice as models for MICPCH syndrome and investigated the effect of CASK mutants." (PMID 37190086, 2023). "We confirmed that female CASK heterozygote KO mice replicate progressive cerebellar hypoplasia observed in MICPCH syndrome." (PMID 37190086, 2023). "A better understanding of the role of CASK in the maintenance of the cerebellar structure may provide insights into the prevention of cerebellar hypoplasia in MICPCH syndrome." (PMID 40422253, 2025). "Female CASK heterozygote KO (CASK-hKO) mice may be the models that mimic the genetic background of most MICPCH syndrome." (PMID 40422253, 2025). "The phenotypes observed in the cerebral cortex in CASK KO mice may be attributable to social deficits, intellectual disability, and infantile spasms in MICPCH syndrome." (PMID 37190086, 2023). "It has been indicated that the transcription mechanism mediated by CASK-Tbr1 is not involved in cerebellar hypoplasia in MICPCH syndrome." (PMID 37190086, 2023).
Ohtahara syndrome (6 papers, 2015 to 2023). "Syndromes associated with CASK mutations, e.g. Ohtahara syndrome, can also arise from respiratory chain defects." (PMID 27036546, 2016). "Finally, boys with CASK mutations may present with Ohtahara syndrome, a type of epileptic encephalopathy displaying a burst‐suppression EEG pattern." (PMID 32696595, 2020). "We conclude that CASK loss-of-function alterations cause severe epileptic encephalopathy in males but do not specifically underlie e.g. Ohtahara syndrome." (PMID 25886057, 2015). "Patients with undetectable CASK protein exhibit prominent cerebellar hypoplasia and electroencephalogram (EEG) defects including multifocal epileptic discharges and burst‐suppression and thus receive the diagnosis of Ohtahara syndrome." (PMID 32696595, 2020).
X-linked intellectual disability (6 papers, 2021 to 2025). An X-linked intellectual deficiency in which not enough information is known, reported or published to indicate whether a gene causes non-syndromic or syndromic presentations. "Furthermore, the YWHAZP10 gene is located next to OTC and CASK, the deletion of which results in hyperammonemia and X-linked intellectual disability, respectively." (PMID 38674334, 2024). "In individuals with MICPCH or X-linked intellectual disability (XLID), over 100 investigations have documented a variety of CASK variants, including missense variants, intragenic duplications, splice site variants, rearrangements, and deletion-insertion variants." (PMID 36092876, 2022).